MYC (MYC proto-oncogene, bHLH transcription factor)
Diseases named in the same sentence as MYC in open-access papers (continued):
Sharing a sentence is not in itself a finding about the gene and the disease.
cancer (continued). "Destruction of c-MYC was attributed to ubiquitin-mediated proteolysis in different cancers." (PMID 26317998, 2015). "Lastly, well known cancer driver genes such as MYC are among the DCGs." (PMID 26030765, 2015). "Many studies have focused on RAS and MYC as cancer-relevant Let-7 targets, although recent high-throughput sequencing (mRNA-seq, miRNA-seq, and CLIP-seq) and meta-analyses indicate that these mRNA targets are not frequently regulated by Let-7, especially in the context of cancer." (PMID 26244988, 2015). "The high level of expression of PIM1 and PIM2 in ABC-DLBCL and the reported synergistic effect of these two kinases with c-MYC in several cancers, prompted us to test the efficiency of the pan-PIM kinase inhibitor AZD1208 in preventing proliferation of aggressive NHL-derived cell lines." (PMID 26643319, 2015). "The intricate network of genes sustaining the oncogenic activity of MYC, the MYC network, if identified, could lead to the development of drugs for cancer therapy." (PMID 25477524, 2015). "A long intergenic noncoding RNA (lincRNA) homologous to the mouse plasmacytoma variant translocation gene (PVT1) is reported to control levels of MYC through regulation of the MYC protein stability and consequently cooperate to promote cancer cell proliferation." (PMID 32309571, 2015). "Through the use of chromosome engineering in mice and both loss and gain-of-function analyses in different human cancer cell lines, it was demonstrated that PVT1 was required for high MYC protein expression, via its capacity to protect MYC from phosphorylation and subsequent degradation." (PMID 27077133, 2015). "Targeting c-MYC could put a brake on the rapid growth of cancer, but c-MYC is currently undruggable." (PMID 26317998, 2015). "PAICS appears to be regulated by MYC in other cancer types, which further emphasizes the important roles this enzyme may play in cancer." (PMID 25869206, 2015). "Given the crucial role of MYC in many cancers, these findings suggest that MYC-regulated lncRNAs and also lncRNAs that regulate MYC could be potential valuable targets in the treatment of many human cancers." (PMID 27077133, 2015). "Enhancer of zeste homolog 2 (EZH2) and HDACs were recently identified as critical histone modifiers of deregulated miRNAs in cancer and can be recruited to a miRNA promoter by transcription factors such as v-myc avian myelocytomatosis viral oncogene homolog (MYC)." (PMID 26703582, 2015). "Somatic mutations in cancer driver genes, tumor suppressors, and amplified oncogenes such as EGFR, RAS, BRAF, MYC, isocitrate dehydrogenase (IDH), and fumarate hydratase (FH) have been shown to be linked to specific alterations in metabolic activity in cancer cells (11, –, 14)." (PMID 26023239, 2015). "Therefore, it is important to devise easily synthesizable and cost-effective c-MYC stabilizers which can exhibit tailored antiproliferative activities in cancer cells." (PMID 26286633, 2015). "In addition to MYC, another two cancer-related molecules MYB and MS4A3 were also significantly down-regulated by all five shikonin derivatives." (PMID 26472107, 2015). "By using Taqman assay, we tested the repression of MYCLo-4∼6 by MYC in various cancer types." (PMID 26003165, 2015). "In addition, posttranscriptional regulation of MYC also contributes on the overexpression of MYC in cancer." (PMID 26003165, 2015). "Silibinin treatment diminishes c-MYC expression, a key regulator of cancer metabolism." (PMID 26510913, 2015). "CKS1B has been shown to overcome the DNA damage response barrier triggered by activated oncoproteins, suggesting that in the context of activated MYC its expression could enhance cancer cell fitness." (PMID 25477524, 2015). "Identification of these MYC “synthetic lethal” pathways might facilitate therapeutic targeting of MYC-driven cancers." (PMID 26416427, 2015).
cancer (continued). "For example, the recent discovery that MYC enhances the transcription of the majority genes in the genome correlates with the fact that several transcription interfering drugs preferentially kill cancer cells." (PMID 24576043, 2014). "This suggests that a large number of human primary cancers may, as far as the MYC-FLIPL regulon is concerned, have the potential to respond to TRAIL." (PMID 24589226, 2014). "Amplification of the MYC oncogene commonly occurs in various types of human cancers." (PMID 25495526, 2014). "Thus, due to MYC’s critical role in human cancer, mounting research efforts have been made to identify potential therapies for MYC-driven cancer." (PMID 25495526, 2014). "Our study demonstrates that inhibition of PRKDC may offer a therapeutic strategy in MYC-driven cancers." (PMID 25495526, 2014). "c-MYC (MYC) is a potent oncogene that is frequently deregulated in a variety of cancers." (PMID 25299775, 2014). "Consistent with this hypothesis, cancer cells overexpressing MYC proteins are addicted to DNA helicase, WRN, which plays an important role in resolving replication stress." (PMID 24728180, 2014). "We hypothesized that since MYC-driven cancer cells may be more dependent on DNA damage pathways, PRKDC is an attractive candidate for a druggable synthetic lethal gene." (PMID 25495526, 2014). "Thus, MYC reduction through pharmacological intervention provides potential strategies to target MYC-driven cancer." (PMID 25495526, 2014). "Another characteristic feature of aggressive cancers is the activation of the MYC oncogene." (PMID 25115192, 2014). "Furthermore, CNAs, as often reported in clinical samples, were detected in the regions of some cancer-related genes; for example, copy number gains of FGFR1, EGFR and PDGFRA in H1703, amplification of MYC and a homozygous loss of CDKN2A in LC2/ad." (PMID 25378332, 2014). "Interestingly both c-MYC and PVT1 are part of the same locus known to be frequently overexpressed in cancer and c-MYC is an important oncogene known to increase cancer cell growth and proliferation." (PMID 24886442, 2014). "Our results suggest that, mechanistically, the synthetic lethality observed between PRKDC suppression and MYC overexpression may in part be due to the reliance of MYC-expressing cancer cells on PRKDC-mediated DNA damage repair." (PMID 25495526, 2014). "Importantly, several reports have shown that 10058-F4 affects c-MYC expression and induces cell cycle arrest, inhibits cell growth, promotes apoptosis and confers chemo-sensitivity in a c-MYC specific manner in various cancer cell types." (PMID 24859015, 2014). "Mutations in the coding region of MYC are not required for oncogenicity and do not play important roles in human cancer, but can enhance the oncogenic potential like in v-myc." (PMID 25326649, 2014). "At the cellular level, MYC-induced γH2AX protein upregulation, a hallmark for DSB and replicative stress where PRKDC has an essential function, suggesting that MYC-driven cancer cells may be more dependent on DNA damage response components." (PMID 25495526, 2014). "MYC is amplified or over-expressed in multiple cancer types leading to up-regulation of many genes controlling cell proliferation, so it is predicted that variation at this locus acts through subtle effects on MYC gene expression." (PMID 24705330, 2014). "Our data suggested synthetic lethality of PRKDC in MYC-overexpressing cancers." (PMID 25495526, 2014). "Given the structural similarity and functional redundancy between MYCN and MYC, R9-caPep might be effective in treating cancers that overexpress MYC as well." (PMID 24728180, 2014). "To assess whether a similar mechanism would operate in the ALDHbright cancer cells as well, we evaluated the levels of microRNA 33a and its target c-MYC in ALDHbright cells, treated with vehicle or metformin, respectively." (PMID 24980829, 2014).
cancer (continued). "The glutamine catabolism could be stimulated by oncogenic transcription factor c-MYC to fuel proliferation of cancer cells through up-regulating glutaminase (GLS)." (PMID 25153931, 2014). "Collectively, our data indicate high levels of MYC are maintained in different cancer cells via distinct mechanisms at the level of transcription elongation with different compliments of transcription factors and are therefore subjected to different JQ1 sensitivity." (PMID 24466310, 2014). "Our study demonstrates that the regulation of high levels of MYC expression in different cancer cells is driven by unique regulatory mechanisms and that such exclusive regulatory signatures in each cancer cells could be employed for targeted therapeutics." (PMID 24466310, 2014). "There were also gene sets related to cancer signaling pathways (MYC, STAT3, and CDH1) or genes moderately involved in cancer (IRF4, SOX4, and EZH2), as well as some associated with various aspects of cancer such as cell transformation, metastasis, and response to therapeutics." (PMID 25122487, 2014). "Synthetic lethality provides an opportunity for therapeutic intervention of MYC-driven cancers." (PMID 25495526, 2014). "Thus, MYC-mediated altered cancer cell energy metabolism can be a potential target for the development of new anticancer therapies." (PMID 24889866, 2014). "As a proof of this, multilayered modulation of metabolic enzymes by known oncogenes and tumor suppressors has been recently unveiled, with more detailed data available regarding the c-MYC-mediated modulation of glycolysis and glutamine metabolism in cancer cells." (PMID 24980829, 2014). "We hypothesize that MYC-overexpressing cancer cells may become more reliant on the DNA damage repair machinery of PRKDC for survival." (PMID 25495526, 2014). "Whether MYC can regulate cellular metabolism in antiestrogen resistant cancers, and whether this is a key component of this phenotype, remain unknown." (PMID 25339305, 2014). "We hypothesized that MYC regulates lactate production through transcriptional regulation, since MYC is an important regulator for cell cycle and glycolysis in cancer cells." (PMID 24928511, 2014). "Our data are consistent with the concept that a MYC centered transcriptomic program is critical for embryonic stem cell maintenance and also accounts for the similarities between embryonic stem cell cell and cancer cell transcriptional programs." (PMID 24796395, 2014). "Thus, a possible scenario is cancer cells that are ‘addicted’ to MYC become highly sensitive to hindrance of PRKDC function, leading to subsequent interference of MYC transcription and protein translation and cancer cell death." (PMID 25495526, 2014). "ESC, PRC and MYC are all properties shared by tumors from several types of cancer." (PMID 25115192, 2014). "CXCR4 and c-MYC are addictive oncoproteins of many malignant tumors." (PMID 25115391, 2014). "IGF2BPs could be exploited in cancer through their influence on classical oncogenes, in particular MYC and KRAS." (PMID 23069990, 2013). "In the light of our findings, diclofenac may represent an attractive novel inhibitor of glycolysis and MYC, which could easily be integrated in clinical trials with likely important implications in cancer therapy." (PMID 23874405, 2013). "Recent papers on the subject have reported the importance of PTEN, IGFs, and MYC in these processes, significantly transcripts also regulated by IGF2BPs, and also that the majority of effected transcripts are shared in both wound healing and cancer." (PMID 23069990, 2013). "ATAD2 expression was higher in non-endometrioid, high-grade and ER negative tumors (p<0.001, p<0.001, and p = 0.02 respectively); high MYC signaling was associated with poorly differentiated (p = 0.0016) and non-endometrioid (p<0.001) cancers." (PMID 23393560, 2013). "The increase in MYC mRNA level in human cancers may result from both direct and indirect mechanisms, which could have several explanations." (PMID 24053468, 2013).
cancer (continued). "Low levels of let-7b and -c have been identified in different subtypes of AML, and the causal relationship of its deregulated expression in cancer can be supported by evidence suggesting it targets a number of genes involved in the cancer process such as KRAS, TRIM71, nRAS, MYC, and HMGA2." (PMID 24416592, 2013). "Several studies showed that MYC inactivation suppresses tumors in animals, suggesting that MYC may be a molecular target in cancer treatment." (PMID 24053468, 2013). "MYC is a transcription factor that is involved in the regulation of a large number of genes and hyperactivation or amplification of the Myc gene occurs in many cancers." (PMID 24137549, 2013). "This may account for some of the effectiveness of HDAC inhibitors as cancer therapeutics, and we found cell lines that were sensitive to knockdown of MYC or ATAD2 were also sensitive to the HDAC inhibitor Trichostatin-A." (PMID 23393560, 2013). "Targeting MYC expression by BET inhibition resulted in antitumoral effects in various cancers." (PMID 24231268, 2013). "The reprogramming factors OCT4, SOX2, NANOG, KLF4, c-MYC, and LIN28 have also been suggested to be oncogenes and may be implicated in the development of several cancers." (PMID 24040120, 2013). "MiR-23a was demonstrated to be transcriptionally repressed by MYC in many cancer cells." (PMID 24261995, 2013). "Moreover, they are highly associated with cancer metastasis and the expression of oncogenic factors (KRAS, MYC and MDR1)." (PMID 23069990, 2013). "Furthermore, MYC is recognized to be the most frequently amplified protein-coding gene across all cancer types." (PMID 23717612, 2013). "However, metabolic differences between MYC-dependent cancer cells and their isogenic differentiated counterparts have not been characterized upon MYC suppression in vitro." (PMID 24280108, 2013). "Deregulated overexpression of MYC is responsible for a wide range of human cancers." (PMID 22848662, 2012). "High levels of MYC protein in cancers may thus reflect impairment of degradation pathways as well as increased transcription." (PMID 22754359, 2012). "This MYC-dependency emphasizes the potential of MYC-specific cancer therapies." (PMID 22860051, 2012). "According to the COSMIC database, the most significant cancer gene in this region is MYC." (PMID 22629346, 2012). "In translational models of solid and hematologic malignancies, the cancer-specific antiproliferative activity of JQ1 has been mechanistically linked to addiction to the BRD4 proto-oncogene or oncogenic MYC (a BRD4 target gene)." (PMID 22901802, 2012). "Furthermore, a connection between MYC (v-myc myelocytomatosis viral oncogene homolog), a master transcription factor and oncogene that is deregulated in many cancers and glutamine metabolism has been described." (PMID 22823888, 2012). "However, MYC is also a powerful inducer of apoptosis, which is one of the major failsafe programs to prevent cancer development." (PMID 22393362, 2012). "Therefore, we will briefly outline the general aspects of MYC’s role in cancer development and present our encounter with this gene in various cancers, particularly in HCC." (PMID 22580498, 2012). "The MYC transcription factors are known to be involved in the biology of many human cancer types." (PMID 21390222, 2011). "Evidently, MYC is one of the most important TFs in both hESCs and Cancer cells." (PMID 22041030, 2011). "MYC regulatory networks may account for most of the transcriptional similarity between embryonic stem cells and cancer cells." (PMID 22041030, 2011). "Since MYC is known to be either over-expressed or amplified in many human cancers, it could be responsible for the decreased levels of NDRG2 mRNA." (PMID 21226903, 2011). "Moreover, for the first time, our analysis identifies this role of Myc in embryonic stem cells, multiple known MYC-driven cancers, and particularly in other previously un-suspected cancers." (PMID 22039435, 2011).
cancer (continued). "The MYC oncoprotein is capable of conferring a selective advantage on cancer cells by stimulating proliferation, cell survival, differentiation blockade, genetic instability and angiogenesis, all of which may contribute to metastasis." (PMID 22075943, 2011). "The oncogene c-MYC is one of the most crucial and frequently deregulated proteins in human cancers." (PMID 21324178, 2011). "Human chromosomal region 8q24 contains several genes which could be functionally related to cancer, including the proto-oncogene c-MYC." (PMID 22142333, 2011). "While genetic alterations in specific human cancers continue to accumulate through deep sequencing, whether key oncogenic hubs, such as the MYC oncogene, behave in a general way or in a context dependent manner remains poorly understood." (PMID 22039435, 2011). "c-MYC sensitizes MB cells to some anti-cancer treatments in vitro." (PMID 21324178, 2011). "In cancer, MYC is often dysregulated, commonly due to genomic abnormalities." (PMID 20930934, 2010). "Efforts to improve the efficacy of this compound could lead to a potentially important way to target MYC/Pim1-expressing cancers." (PMID 20515470, 2010). "This raises the intriguing hypothesis that deregulation of MYC expression may be connected to the increased cancer proneness of XP patients." (PMID 20840796, 2010). "These genetic changes include CDKN2A deletion and MYC amplification in immortalization, HRAS activation in transformation, PIK3CA activation in the formation of malignant tumors, and RUNX1 deletion associated with poorly-differentiated malignant tumors." (PMID 20169162, 2010). "Indeed, hTERT or telomerase inhibition compromises sustained proliferation and tumorigenic ability of cancer cells while the c-MYC-mediated cellular transformation is severely attenuated if without Pontin and Reptin." (PMID 20509972, 2010). "Interestingly, both CCNE2 and MAL2 are located on chromosome 8q, a region which is frequently increased in copy number in breast and other cancer types, and one of the most important target genes affected by gains and amplifications of 8q is the MYC oncogene." (PMID 21129172, 2010). "The effect of these mutations are highly variable and while some cells or tissues may experience reduced MYC activity and thus reduced proliferation, elsewhere the overexpression of this oncogene may trigger cancer." (PMID 20840796, 2010). "Such defective clonogenesis may be attributable to down-regulation of hTERT expression and telomerase activity, impaired c-MYC function and/or down-regulation, and growth arrest taking place in Reptin-depleted cancer cells." (PMID 20509972, 2010). "Taken together with the co-expression of high levels of MYC and Nkx3.1 in the more advanced invasive carcinomas from Lo-MYC mice, these results suggest that the large effects on downregulation of Nkx3.1 by MYC only occurs in PIN lesions, with less of an effect in pre-invasive and invasive lesions." (PMID 20195545, 2010). "The role of MYC amplification in ovarian and other cancers is well established." (PMID 19240718, 2009). "Similarly, approximately the highest quartile was selected for MYC, reflecting the expected proportion of cancers that would probably have amplification of the gene." (PMID 18373870, 2008). "Thus, HSPC111 over-expression appears to be a common feature of many cancers but its relationship to aberrant Myc function, which is only contributed in part by MYC mRNA levels, remains to be elucidated." (PMID 18373870, 2008). "The mutant forms of the MYC protein found in these cancer fail to induce BIM [see ref below]." (PMID 19458766, 2007). "CDCA7 is a downstream target of MYC and is frequently overexpressed in human cancers." (PMID 18059402, 2007). "Aberrant TCF7L2 expression modifies Wnt signaling and mediates oncogenic effects through the upregulation of c-MYC and cyclin D. Genetic alterations in TCF7L2 may therefore affect cancer risk." (PMID 17109766, 2006).